ACE (angiotensin I converting enzyme)
Diseases named in the same sentence as ACE in open-access papers (continued):
Sharing a sentence is not in itself a finding about the gene and the disease.
diabetes (continued). "We cannot exclude the possibility that diabetes changed expression of ACE, ACE2, NEP, or other enzymes that affect ANG II formation or decomposition." (PMID 27803936, 2016). "Human and animal studies showed that ACE inhibitors and ARBs have positive effect on glucose disposal in glucose intolerance, diabetes mellitus, obesity, and hypertension." (PMID 27413253, 2016). "A first prescription of ACE-inhibitors was to a larger extent filled by men than women (P < 0.001) and by patients with diabetes (P < 0.001)." (PMID 27749548, 2016). "On bivariate analysis, factors significantly associated with DES use included: diabetes, private insurance, coronary artery disease (CAD), hyperlipidemia, aspirin use, ACE-inhibitor or ARB use, beta-blocker use, and statin use." (PMID 26106504, 2015). "Several studies have also shown that ACE inhibition reduced the accumulation of serum AGEs in diabetes, possibly via effects on oxidative pathways." (PMID 26491434, 2015). "ACE inhibitor/ARB use was also determined in participants with diabetes, of whom 50.8% were taking this class of medications." (PMID 26171960, 2015). "Aldosterone antagonists are indicated in patients receiving beta-blockers plus ACE inhibitors or ARBs after myocardial infarction who have left ventricular systolic dysfunction and either heart failure or diabetes mellitus." (PMID 26718096, 2015). "The ACE-Ang II-AT1 receptor axis is detrimental to vascular function in diabetes where it mediates vasoconstriction, oxidative stress and pro-inflammatory signaling." (PMID 26536590, 2015). "As recalled above, ACE inhibitors share the protective effect of ARBs against diabetes induced endothelial dysfunction and peripheral neuropathy, and would thus be expected to be as effective to restore PIV." (PMID 25888905, 2015). "The ability of the extracts to inhibit diabetes enzymes in rat pancreas as well as the inhibition of angiotensin-1-converting (ACE) enzyme in lungs homogenates in vitro were investigated." (PMID 25598760, 2014). "We also noted that these patients were less likely to be receiving some other medications like statins, aspirin and ACE inhibitors than patients with diabetes on medication indicating that these patients were receiving less secondary cardiovascular protection." (PMID 25361884, 2014). "Previous investigations have suggested a genetic predisposition of ACE I/D polymorphism with CAD, CVD, diabetes mellitus However, there were significant inter-ethnic variations." (PMID 24679048, 2014). "It was −3.96±0.89 (TT), −1.57±1.05 (TC) and −0.64±1.12 ml/min.year−1 (CC) (mean ± SEM, ANCOVA p = 0.003, adjusted for sex, age, duration of diabetes, and treatment by ACE inhibitors)." (PMID 24819633, 2014). "The major findings of this study were that diabetes led to an upregulation in ACE, ROCK1, ROCK2, and omega-hydroxylase proteins and a downregulation in ACE2 protein that was accompanied by abnormal vascular reactivity in the rat CC." (PMID 25309930, 2014). "ACE inhibitors were used more widely in patients older than 50 years (66.4%) and in those with diabetes (82%)." (PMID 24444396, 2014). "In patients with diabetes (14.3% of the cohort), the benefit was consistent for those patients on ACE inhibitors (adjusted OR 0.29, 95% CI 0.13 to 0.65)." (PMID 25353172, 2014). "Patients with diabetes were more likely to be on an ACE inhibitor or ARB compared to a CCB, and were more likely to be on a CCB compared to a thiazide." (PMID 25353172, 2014). "We reported that a renin inhibitor was more effective than an ACE inhibitor or ARB in preventing diabetes-induced cardiac superoxide production, apoptosis and fibrosis, suggesting the intracellular RAS as a possible residual risk factor in diabetes." (PMID 24215514, 2013).
diabetes (continued). "In contrast to nondiabetic hearts, Capt + Los dual therapy was the most effective therapy (alongside Triple therapy) in diabetic hearts which is consistent with the known diabetes-induced overactivity of the ACE/Ang II/AT1 signaling cascade." (PMID 24066305, 2013). "Recently, in diabetes mellitus, early detection of proteinuria and treatment with angiotensin-converting enzyme (ACE) inhibitors has been shown to slow progression of kidney disease and to improve prognosis." (PMID 23446441, 2013). "Lowering renal-vascular tissue-RAS activity in pathologic states such as diabetes and obesity with conventional pharmacotherapy (ACE inhibitor or angiotensin receptor blocker) has shown efficacy for the primary prevention of diabetic nephropathy." (PMID 23971740, 2013). "We report that AT1a-KO mice develop diabetes-induced cardiac dysfunction, which is prevented by a renin inhibitor, as well as by an ACE inhibitor and ARB." (PMID 24215514, 2013). "Others and we have shown prevention of cardiac dysfunction by ARBs and ACE inhibitors in animal models of diabetes." (PMID 24215514, 2013). "In a meta-analysis of 18 studies evaluating thousands of patients in total, it was concluded that ACE inhibitors decelerate progression to diabetes." (PMID 24072084, 2013). "There were 13 patients on sole ACE inhibitor therapy, out of which 6 were having diabetes mellitus and 7 had uncontrolled blood pressure." (PMID 24053215, 2013). "Overall, 1277 patients used diabetes medications, 1030 used ACE inhibitors, and 638 used ARBs during the case or control periods." (PMID 23912052, 2013). "Our results showed that rats with STZ-induced diabetes had higher expression of ACE and lower expression of ACE2 in the kidney compared with the control rats." (PMID 23658831, 2013). "Men with diabetes are significantly more likely to receive oral combination drugs, ACE inhibitors and calcium channel blockers in the presence of coronary heart disease, respectively." (PMID 22838970, 2012). "Men with diabetes were significantly more likely to receive oral combination drugs, ACE inhibitors and calcium channel blockers in the presence of coronary heart disease." (PMID 22838970, 2012). "Our results demonstrate that men with diabetes were significantly more likely to receive oral combination drugs, ACE inhibitors and calcium channel blockers for CHD than women." (PMID 22838970, 2012). "In the same study, the use of ACE inhibitors (or ARBs) in 103 patients with diabetes and CKD was only 34%." (PMID 23369274, 2012). "Significant gender differences in ACE inhibitors in CHD patients with diabetes sustained after adjusting for age, Hba1c, appointements with GP, medication adherence and comorbidities that are indications for renin-angiotensin system (RAS) blockade." (PMID 22838970, 2012). "Adults with diabetes tended to be older, were more likely to be male, were largely insured by Medicare, had higher BMI and co-morbidity scores, were more likely to use ACE inhibitors, and used medical “well care” examinations less frequently." (PMID 22776352, 2012). "An increased renal vasodilator response to ACE inhibition or Ang II blockade in diabetic patients has been interpreted as evidence that the intrarenal RAS is activated in diabetes." (PMID 21915376, 2011). "Prescribing trends were similar in people also taking diabetes medications or ACE inhibitors to the rest of the population." (PMID 21733195, 2011). "There was some evidence of interaction between genetic polymorphisms and cardiovascular risk factors (ACE and high-density lipoprotein; VDR and diabetes) on brain volume decline." (PMID 22028967, 2011). "The majority (>90%) of heart failure patients with reduced ejection fraction (SHF) and diabetes were treated with an ACE inhibitor (ACEi) or angiotensin receptor blocker (ARB) or with beta-blockers." (PMID 21303531, 2011).
diabetes (continued). "Patients receiving ACE-inhibitors had the highest rates of heart failure, atrial fibrillation, diabetes and angina at baseline." (PMID 22028911, 2011). "Cox regression multivariate analysis showed that DD polymorphism of ACE gene, 4G/4G polymorphism of PAI-1 and diabetes mellitus are independent prognostic risk factors of CAD." (PMID 28352370, 2010). "The DD polymorphism of ACE gene, 4G/4G polymorphism of PAI-1 gene as well as diabetes mellitus, are the independent prognostic factors of CAD." (PMID 28352370, 2010). "In streptozotocin-induced diabetes in rats, the PPARα agonist bezafibrate and the PPARγ ligand pioglitazone can equally protect against the streptozotocin-induced upregulation of ACE in the aortic wall." (PMID 20613959, 2010). "The presence of diabetes predicts the use of ACE inhibitors, whereas the diagnosis of unstable angina and ST-elevation myocardial infarction predict the use of statin." (PMID 21577376, 2010). "CAD patients with diabetes mellitus, DD genotype of ACE, and 4G/4G genotype of PAI-1 suggested poor prognosis." (PMID 28352370, 2010). "Patients with diabetes were more likely to receive a diuretic plus an angiotensin II receptor antagonist than an ACE inhibitor plus a diuretic (28.4% versus 25.1%)." (PMID 20003298, 2009). "Diabetes-preventive benefits have also been claimed by a number of previous studies with angiotensin-converting enzyme (ACE) inhibitors." (PMID 20165647, 2009). "This review focuses on the potential roles of rosiglitazone, a member of TZD class of antidiabetic agents, and ramipril, an ACE inhibitor, in preventing the preclinical macrovasculopathy in diabetes and IGT population." (PMID 20165647, 2009). "The ADaPT investigation ("ACE inhibitor-based versus diuretic-based antihypertensive primary treatment in patients with pre-diabetes") is a 4-year open, prospective, parallel group phase IV study." (PMID 18652658, 2008). "Thus, ACE gene polymorphisms may play a role in the pathogenesis of chronic pancreatitis and several other pancreatic diseases including acute pancreatitis, pancreatic cancer, diabetes mellitus and cystic fibrosis." (PMID 17163998, 2006). "Caucasian patients with insulin-dependent diabetes mellitus and normoalbuminuria (83% in DD, 87% in DI and 81% in II) at baseline showed comparable treatment effects from ACE inhibitors between genotypes within the first 12 months." (PMID 16242049, 2005). "However, these disturbances of the myocardial Ca2+i transient in diabetes were effectively counteracted by the ACE inhibitor Enalapril or the AT1R receptor antagonist Losartan treatment." (PMID 40149735, 2025). "ACE and Renin inhibitorAnti-hypertensionDPP IV inhibitorAnti-hyperglycemia(anti-diabetes)." (PMID 41585459, 2025). "Accordingly, patients with diagnosis of diabetes were more frequently taking guideline-conforming medication for cardiac conditions (eg, ACE inhibitor or angiotensin II receptor blocker, mineralocorticoid receptor antagonist, diuretic, statin, platelet inhibitor, or oral antidiabetics)." (PMID 40737012, 2025). "Interestingly, the results of six large-scale clinical studies have reported a remarkably consistent 14–34% reduction in the incidence of diabetes in hypertensive patients treated with ACE inhibitors for 3–6 years." (PMID 39342254, 2024). "Notably, the ASCVD group had a higher prevalence of myocardial infarction, while all statin-benefit groups had a higher prevalence of obesity, diabetes with chronic complications, and tobacco use but lower ACE inhibitors use in post-guideline." (PMID 38730371, 2024). "Additionally, certain medications commonly used in diabetes management, such as angiotensin-converting enzyme (ACE) inhibitors or angiotensin II receptor blockers (ARBs), can further inhibit potassium excretion, compounding the risk." (PMID 39176183, 2024). "This suggests that the coadministration of ACE inhibitors and allopurinol could be promising in diabetes prevention and cardiovascular conditions." (PMID 38333456, 2024).
diabetes (continued). "ACE inhibitors are protective for diabetes whereas BBs showed adverse effects." (PMID 39567981, 2024). "However, it is almost certainly not appropriate to exclude all older people, all people with diabetes, and all people taking antihypertensive drugs, such as ACE inhibitors and angiotensin II receptor blockers." (PMID 38284271, 2024). "Moreover, diabetes mellitus and the combination of ACE I/D and AGTR1 rs5182 variations were predictors of TG and TG/HDL-C exclusively in females." (PMID 39080710, 2024). "The harmful effects of diabetes in SHRDI rats could be prevented by the chronic inhibition of ACE with enalapril or by blockade of an AT1R antagonist (olmesartan)." (PMID 38279313, 2024). "Materials and Methods: Sanger DNA sequencing of the exons of CBR1, GLO1, and ACE genes was conducted in 113 patients with early and severe DN (defined as occurring within 10 years of the diagnosis of diabetes and with eGFR < 45 mL/min/1.73 m2) and 100 controls." (PMID 39336582, 2024). "Thus ACE-2 is targeted in many treatments for controlling diabetes including ACE inhibitors medications, endogenous ACE-2 activators, ACE-2 gene therapies, human recombinant ACE-2, and Ang-II receptor blockers." (PMID 37456637, 2023). "In der ACCOMPLISH-Studie wurde allerdings bei 6000 Patient:innen mit Typ 2 Diabetes und Hypertonie nachgewiesen, dass bei gleichen Blutdruckzielwerten (135/80 mm Hg) die Kombination von ACE-Inhibitoren mit Amlodipin der Kombination von ACE-Inhibitoren und Hydrochlorothiazid deutlich überlegen war." (PMID 37101036, 2023). "This study suggested that patients with MetS might be at a lower risk of developing diabetes when treated with a combination of CCB (verapamil) and angiotensin-converting enzyme (ACE) inhibitor (trandolapril)." (PMID 38089047, 2023). "While the antifibrotic mechanism of ACE inhibitors and ARBs did not significantly affect the rate of requiring surgical intervention, male gender, obesity, younger age, and diabetes, all increased the risk for operative intervention." (PMID 37719830, 2023). "Die aktuellen ESC Leitlinien zur kardiovaskulären Prävention empfehlen einen ACE Hemmer oder Angiotensin Rezeptor Blocker unabhängig vom Vorliegen eines Diabetes als Antihypertensivum der ersten Wahl, die aktuellen Leitlinien der ADA empfehlen einen ACE Hemmer bzw." (PMID 37101036, 2023). "These concepts have recently been highlighted by the new guidelines on diabetic kidney disease (DKD), which recommend treatment with angiotensin-converting enzyme (ACE) inhibitors or angiotensin II receptor blockers (ARBs) for CKD patientswith diabetes and albuminuria." (PMID 35583597, 2022). "Since diabetes-induced changes in the intestine may be partly reversed by enalapril, intestines may be a therapeutic target for ACE inhibitors." (PMID 35682739, 2022). "Risk factors for developing contrast nephrotoxicity include pre-existing CKD, dehydration, diabetes, and the use of ACE inhibitors, diuretics, and NSAIDs, all common situations in older patients providing high susceptibility to developing worsening kidney function." (PMID 36186775, 2022). "Other studies listed similar and further risk factors for development of AKI: the use of angiotensin-converting-enzyme (ACE) inhibitors or angiotensin receptor blockers, chronic kidney disease, advanced age, diabetes, hypertension, myocardial infarction, hip arthroplasty, and others." (PMID 39036514, 2022). "Plasma ACE levels were shown to be higher in people with diabetes (p<0.05)." (PMID 36110446, 2022). "ACE2/Ang1-7 and ACE/AngII are bound to have a state of dynamic balance disorder in the development of diabetes, which may be related to the influence of high blood glucose on the systemic inflammatory response and immune system dysfunction." (PMID 36253996, 2022).
diabetes (continued). "Blockade of the renin-angiotensin system with ACE inhibitors has already been shown to have analgesic effects in humans and in several models of neuropathic pain induced by chronic constriction injury, insulin resistance, or streptozotocin-diabetes." (PMID 35456682, 2022). "As further examples, ACE inhibitors were also found to be protective for “other specified joint diseases” even though joint pain is a known side effect, and thiazides were estimated to be protective for diabetes, also a known side effect." (PMID 35689299, 2022). "In experimental diabetes there is an increase in ACE expression in different tissues, which can explain why patients with diabetes may have more severe disease." (PMID 33648564, 2021). "Moreover, ACE inhibition with the ACE-I ramipril in diabetes decreased the both adverse cardiovascular and renal outcomes." (PMID 34570768, 2021). "Guidelines recommend a renin-angiotensin system (RAS) blocker ACE inhibitor (ACEI) or angiotensin receptor blocker (ARB) for the treatment of hypertension in people with diabetes mellitus, particularly in the presence of microalbuminuria, albuminuria, proteinuria, or left ventricle hypertrophy." (PMID 33859687, 2021). "The activity of ACE is high in the lungs in mouse models of diabetes." (PMID 33859687, 2021). "A protective effect of ACE blocking was evident in pre-existing diabetes but not in COVID-associated hyperglycaemia." (PMID 34439986, 2021). "And functional polymorphisms in the ACE, AGT, and AGTR1 can impact the expression or the function of encoded proteins, and are related to stroke, coronary heart disease, vascular dysfunction and diabetes." (PMID 34150864, 2021). "Third, a substantial portion of participants in this study had comorbidities of diabetes or cardiovascular diseases, and might have taken other concomitant medication, such as metformin, ACE inhibitors and angiotensin II receptor blockers (ARB)." (PMID 34096808, 2021). "Among those hospitalized, a large percentage are likely being administered either ACE inhibitors or Angiotensin II blockers, since epidemiological data reveal that cardiomyopathies, diabetes mellitus, and hypertension are the most frequent comorbidities found among those patients." (PMID 34440107, 2021). "Therefore, ACE activity inhibition has been used to prevent and treat various diseases like heart failure, myocardial infarction, nephropathy, and even diabetes." (PMID 32610462, 2020). "Thus, it is likely that diabetes and hypertension, cured by ACE inhibitors, are comorbidities contributing to the unfavourable progression of COVID-19 infection." (PMID 33203793, 2020). "In our sample, in order to further investigate the potential beneficial effects of ACE inhibitors, the impact of which might be larger in patients with diabetes, COPD, or cardiovascular diseases, we performed additional analyses, stratified by comorbidities." (PMID 32579597, 2020). "For example, beta-blockers, angiotensin-converting enzyme (ACE)-inhibitors or angiotensin II receptor blockers (ARBs), and calcium channel blockers can be preferentially used in patients with prior myocardial infarction, diabetes, and angina, respectively." (PMID 32230834, 2020). "However, because a considerable proportion of hypertensive patients with diabetes cannot achieve the target BP or adequate end-organ protection with ARB or ACE inhibitors alone, add-on antihypertensive medications are required." (PMID 31239535, 2019). "However, the most beneficial antihypertensive agents for reducing the progression of diabetic nephropathy in diabetes patients are ACE inhibitors and ARBs2,15." (PMID 31799289, 2019). "Renin–angiotensin–aldosterone system (RAAS) blockade with an angiotensin converting enzyme (ACE) inhibitor (ACEI) or angiotensin II type I receptor blocker (ARB) is the most widely used strategy to slow the progression of DKD in both type 1 diabetes mellitus or T2DM." (PMID 29665833, 2018).